DPEP1 (dipeptidase 1)
Description:
Hydrolyzes a wide range of dipeptides including the conversion of leukotriene D4 to leukotriene E4. Hydrolyzes cystinyl-bis-glycine (cys-bis-gly) formed during glutathione degradation. Also possesses beta lactamase activity and can hydrolyze the beta-lactam antibiotic imipenem. Independently of its dipeptidase activity, acts as an adhesion receptor for neutrophil recruitment from bloodstream into inflamed lungs and liver.
Synonyms: MDP; RDP; MBD1
Tractability: Small molecule: an approved drug acts on it; a structure with a bound ligand is known; it belongs to a druggable protein family. Antibody: UniProt places it where antibodies can reach, with high confidence; its Gene Ontology location is reachable by antibodies, with high confidence; UniProt predicts a signal peptide or a membrane-spanning region. PROTAC: ubiquitination databases record sites on it; a small molecule that binds it is known.
Target class: Protease; Metallo protease; Metallo protease MJ clan; Metallo protease M19 family; Enzyme
Gene: Protein-coding gene on chromosome 16 (89,613,308 to 89,638,456, forward strand). Ensembl gene ENSG00000015413.
Subcellular location: Apical cell membrane; Cell projection, microvillus membrane
Subcellular location (Human Protein Atlas): Cell Junctions; Nucleoplasm
Pathways (Reactome):
Metabolism: Aflatoxin activation and detoxification; Synthesis of Leukotrienes (LT) and Eoxins (EX)
Disease: LTC4-CYSLTR mediated IL4 production
Gene Ontology:
Molecular function: beta-lactamase activity; dipeptidase activity; metallodipeptidase activity; modified amino acid binding; protein binding; zinc ion binding; GPI anchor binding; metalloexopeptidase activity
Biological process: antibiotic metabolic process; homocysteine metabolic process; leukotriene D4 catabolic process; negative regulation of cell migration; cellular response to calcium ion; cellular response to nitric oxide; glutathione catabolic process; glutathione metabolic process; lactam catabolic process; inflammatory response; leukotriene metabolic process; neutrophil chemotaxis; proteolysis
Cellular component: apical part of cell; apical plasma membrane; cell junction; extracellular exosome; plasma membrane; extracellular region; microvillus membrane
Genetic constraint (gnomAD): Loss-of-function variants: 50 observed, 42.04 expected, observed/expected ratio (o/e) 1.19, 90% interval 0.95 to 1.5. The synonymous counts are far from expectation, so gnomAD's model fits this gene poorly and the ratio says little. Missense variants: 663 observed, 572.5 expected, observed/expected ratio (o/e) 1.16, 90% interval 1.09 to 1.24. Synonymous variants: 297 observed, 242.27 expected, observed/expected ratio (o/e) 1.23, 90% interval 1.11 to 1.35.
Homologues: Orthologues: macaque DPEP1 (95% identical), chimpanzee DPEP1 (92% identical), rabbit DPEP1 (81% identical), pig DPEP1 (80% identical), dog DPEP1 (78% identical), guinea pig DPEP1 (76% identical), rat Dpep1 (74% identical), mouse Dpep1 (72% identical), tropical clawed frog dpep1 (60% identical), zebrafish dpep1 (55% identical), Drosophila melanogaster CG6154 (47% identical), Drosophila melanogaster CG44837 (39% identical). Paralogues in human: DPEP2 (45% identical), DPEP3 (44% identical).
Diseases named in the same sentence as DPEP1 in open-access papers:
DPEP1 is named in the same sentence as 82 diseases in open-access papers, as found by Europe PMC text mining. Sharing a sentence is not in itself a finding about the gene and the disease. The quoted sentences say what the papers report.
colon cancer (10 papers, 2012 to 2025). "Recently, single‐cell RNA sequencing indicated that DPEP1 plays a key role in the evolution from ulcerative colitis to ulcerative colitis‐associated colon cancer." (PMID 35670012, 2023). "DPEP1 expression caused a significant increase in colon cancer cell adhesion and invasion in vitro, and metastasis in vivo." (PMID 26824987, 2016). "Consistent with our findings, some reports show that DPEP1 mRNA is highly expressed in colon tumors compared to matched normal mucosa, and its expression is associated with the histological stage of colon cancer." (PMID 26824987, 2016). "This study showed that DPEP1 was highly expressed in colon cancer tissues, which was consistent with previous studies." (PMID 35670012, 2023). "In 41 pairs of colon cancer tissues and adjacent normal tissues, DPEP1 was markedly highly expressed in cancer tissues." (PMID 35670012, 2023). "Functionally, DPEP1 expression increased the resistance of colon cancer cells to the chemotherapy drugs oxaliplatin and irinotecan in the ASCL2‐dependent manner." (PMID 35670012, 2023). "Immunohistochemistry images downloaded from The Human Protein Atlas database further confirmed that DPEP1 was highly expressed in colon cancer tissues." (PMID 35670012, 2023). "In this study, colon cancer data in the the cancer genome atlas (TCGA) and GEO databases were analyzed through bioinformatics analysis, and DPEP1 was found to be highly expressed in colon cancer." (PMID 35670012, 2023). "Survival analysis was performed using the survival package in R software to assess the prognostic value of DPEP1 expression in colon cancer." (PMID 35670012, 2023). "Bioinformatics analysis showed that ASCL2 and DPEP1 were both markedly expressed in colon cancer tissues and had a significantly positive correlation." (PMID 35670012, 2023). "In colorectal cancer, DPEP1 expression is upregulated, the DPEP1 high‐expression group shows a poor prognosis, and DPEP1 is considered a specific tumor marker for colon cancer." (PMID 35670012, 2023). "In summary, DPEP1 binds to ASCL2 in colon cancer cells and enhances protein ASCL2 stability by inhibiting its ubiquitin‐proteasomal degradation." (PMID 35670012, 2023). "Collectively, colon cancer tissues expressed high levels of DPEP1, which was negatively correlated with DSS in colon cancer patients." (PMID 35670012, 2023). "To better understand the possible role of DPEP1 in colon cancer tumors, we first explored the expression levels of DPEP1 in pan‐cancer tissues, DPEP1 expression data from TCGA and GTEx databases were analyzed." (PMID 35670012, 2023). "DPEP1 is frequently dysregulated in many tumors, including colorectal cancer, colon cancer, and breast cancer." (PMID 31541079, 2019). "Clone 10-1 was located and shown to overlap with DPEP1 gene which promoted metastasis in colon cancer but inhibited tumor cell invasiveness in pancreatic ductal adenocarcinoma." (PMID 28410206, 2017). "This discrepancy from previous studies suggests there are different roles for DPEP1 in the progression of colon cancer compared with other cancers." (PMID 26824987, 2016). "To investigate the mechanism regulating DPEP1 expression in colon cancer, we examined the levels of DPEP1 mRNA and protein in the presence of TGF-β1 in the SW480 and SW620 colon cancer cell lines." (PMID 26824987, 2016). "The present study was designed to uncover the putative role of DPEP1 in the progression of colon cancer." (PMID 26824987, 2016). "The present study has revealed DPEP1 as a mediator for colon cancer progression that promotes cancer cell invasion and metastasis by regulating E-cadherin plasticity." (PMID 26824987, 2016). "The expression of DPEP1 mRNA and proteins were upregulated in colon cancer tissues compared to normal mucosa." (PMID 26824987, 2016). "In the current study, we provide evidence regarding the molecular mechanism by which DPEP1 regulates colon cancer metastasis." (PMID 26824987, 2016).
colon cancer (continued). "The results of the current study provide strong evidence that DPEP1 functions as a positive regulator for metastasis in colon cancers." (PMID 26824987, 2016). "In this study, we demonstrate that DPEP1 functions as a positive regulator for colon cancer cell metastasis." (PMID 26824987, 2016). "This resulted in the identification of two upregulated genes (DPEP1 and MMP11) as mutated in colon cancer and another three protease genes mutated in breast cancer (TMPRSS3, ADAM12 and MMP10)." (PMID 24243807, 2013). "Interestingly, we found that ASCL2 expression was significantly positively correlated with that of DPEP1 in colon cancer tissues." (PMID 35670012, 2023). "In contrast, DPEP1 is highly expressed in leukemia cells, hepatoblastoma cells, and colon cancer cells and promotes tumor progression, suggesting that DPEP1 might act as an oncogene in these cancers." (PMID 35670012, 2023). "And DPEP1 expression correlated with poor disease‐specific survival (DSS) in colon cancer patients." (PMID 35670012, 2023). "In conclusion, ASCL2 upregulated DPEP1 expression levels in colon cancer cells." (PMID 35670012, 2023). "RT-PCR analyses showed that DPEP1 mRNA was expressed in 8 of 12 colon cancer cell lines." (PMID 26824987, 2016). "Together, these finding led us to hypothesize that DPEP1 expression may influence the malignant progression of human colon cancer cells." (PMID 26824987, 2016). "We propose that DPEP1 could be a potential therapeutic target as well as a prognostic marker for colon cancer." (PMID 26824987, 2016). "In addition, DPEP1 proteins were expressed in 7 colon cancer cell lines, including LS174T, KM12C, SW48, SW620, DLD-1, LoVo, and COLO205." (PMID 26824987, 2016). "In contrast, DPEP1 is highly expressed in colon tumors as compared to matched normal mucosa." (PMID 26824987, 2016). "Moreover, DPEP1 promotes colon cancer cell proliferation, metastasis, and invasion." (PMID 35670012, 2023). "The results demonstrated that both DPEP1 and ASCL2 were highly expressed in colon cancer tissues compared to normal tissues." (PMID 35670012, 2023). "We then transfected HCT116 cells with pCMV or pCMV‐DPEP1, respectively, and the results indicated that overexpression of DPEP1 resulted in a significant increase in the expression of ASCL2 colon cancer cells." (PMID 35670012, 2023). "RAPH1, SOX14, DPEP1, and UBL4A have a significant role in the invasion or metastasis of breast cancer, cervical cancer, colon cancer, and pancreatic ductal adenocarcinoma, respectively." (PMID 37378426, 2023). "Bioinformatics analysis and experiments showed that the expressions of DPEP1 and ASCL2 in colon cancer tissues were markedly positively correlated." (PMID 35670012, 2023). "Bioinformatics analysis found that DPEP1 expression correlated negatively with DSS in colon cancer patients but not with OS." (PMID 35670012, 2023). "MTT assays were used to evaluate the role of DPEP1 and ASCL2 in colon cancer drug resistance." (PMID 35670012, 2023). "There was a significantly positive correlation between the expression of DPEP1 and ASCL2 in colon cancer, according to which we speculated that there was a mutual regulatory relationship between them." (PMID 35670012, 2023). "Given most reports indicated that ASCL2 was involved in the development of colon cancer as a transcription factor, we first explored whether ASCL2 regulated the expression of DPEP1." (PMID 35670012, 2023). "Furthermore, DPEP1 also could enhance the expression of colon cancer stem cell markers (LGR5, CD133, and CD44), which strengthened the tolerance of colon cancer cells to chemotherapy drugs." (PMID 35670012, 2023). "Therefore, DPEP1/ASCL2 could form a positive feedback loop regulation to maintain high expression levels of DPEP1 and ASCL2 in colon cancer cells, which may explain why DPEP1 induced an increase in drug resistance in colon cancer cells in an ASCL2‐dependent manner." (PMID 35670012, 2023).
colon cancer (continued). "However, DPEP1 is highly expressed in colon tumors compared to matched normal mucosa." (PMID 22363658, 2012). "Interestingly, DPEP1 mRNA and proteins were detected in SW620, but not SW480 cells, two cell lines derived from different stages of colon cancer in the same patient." (PMID 26824987, 2016).
colorectal cancer (10 papers, 2017 to 2025). A primary or metastatic malignant neoplasm that affects the colon or rectum. "Dipeptidase-1 (DPEP1) is highly upregulated in colorectal cancer (CRC), with its enzymatic function linked to invasion and metastasis." (PMID 40178918, 2025). "On the other hand, DPEP1 encodes a dipeptidase whose expression has already been reported to be increased in colorectal cancer samples, along with evidence suggesting a role in conferring drug resistance underscoring its relevance in tumoral processes." (PMID 38975894, 2024). "Meanwhile, loss of expression of DPEP1 as a tumor suppressor gene is associated with colorectal cancer and Wilms’ tumor." (PMID 33193579, 2020). "DPEP1 is found to be a key gene in colorectal cancer tumor formation and maintaining microsatellite stability, impacting neutrophil and CD8+ T cell recruitment." (PMID 40178918, 2025). "DPEP1 was prominently up‐regulated in colorectal cancer during the transition from low‐grade to high‐grade intraepithelial neoplasia and functioned as a positive regulator for metastasis by regulating E‐cadherin expression." (PMID 37378426, 2023). "DPEP1 is a marker for the transition from low-grade to high-grade intraepithelial neoplasia and is proved to be an adverse prognostic factor in colorectal cancer." (PMID 35470736, 2022). "In the study of colorectal cancer, Eisenach found that the expression of DPEP1 was essentially increased in colorectal cancer tissues compared with normal mucosa." (PMID 32068233, 2020). "Studies have shown that the expression of DPEP1 is reduced in invasive and in situ lobular carcinoma of the breast and pancreatic ductal adenocarcinoma and is highly expressed in colorectal cancer and hepatoblastoma." (PMID 34490047, 2021). "DPEP1 has been identified as a prognostic gene for colorectal cancer." (PMID 32068233, 2020). "LINC01315 was also found to be correlated with DPEP1, KRT23, ASCL2, AXIN2, and DUSP4 in colorectal cancer." (PMID 35470736, 2022).
breast carcinoma (9 papers, 2012 to 2024). "For example, DPEP1 expression deficiency was associated with breast cancer and Wilms’s tumor." (PMID 36186450, 2022). "Loss of DPEP1 expression was associated with breast cancer and Wilms' tumor." (PMID 22363658, 2012). "Moreover, DPEP1 acts as a tumor suppressor gene in breast cancer." (PMID 35670012, 2023). "Screening of breast cancer cell lines showed that the mRNA expression levels for the PHKG2 and DPEP1 were lower in non-tumorigenic mammary epithelial cell MCF10A, but elevated in other cell lines." (PMID 28410206, 2017).
pancreatic ductal adenocarcinoma (8 papers, 2012 to 2023). An infiltrating adenocarcinoma that arises from the epithelial cells of the pancreas. "While in pancreatic ductal adenocarcinoma, DPEP1 was negatively associated with the histological grade and invasion of tumour cells." (PMID 37378426, 2023). "DPEP1 expression is also negatively associated with the histological grade of pancreatic ductal adenocarcinoma, and its overexpression suppresses tumor cell invasiveness and enhances chemosensitivity of this cancer." (PMID 26824987, 2016). "For example, DPEP1 is reduced in pancreatic ductal adenocarcinoma, inhibits the invasiveness of tumor cells, enhances chemosensitivity, and predicts a better clinical outcome." (PMID 35670012, 2023).
hepatoblastoma (6 papers, 2019 to 2025). Hepatoblastoma (HB) is a malignant hepatic tumor and is the most common pediatric liver cancer. "The miR-193a-5p/DPEP1 axis regulates hepatoblastoma progression via the PI3K/Akt/mTOR signaling pathway." (PMID 40161373, 2025). "Studies have shown that DPEP1 can promote hepatoblastoma progression and leukemia cell proliferation." (PMID 35670012, 2023). "Recent transcriptome analyses have unveiled that the genes GATA4, DPEP1 and DRAM1 exhibit high expression levels in hepatoblastoma tumor samples." (PMID 38390281, 2024).
acute kidney injury (4 papers, 2020 to 2025). Sudden and sustained deterioration of the kidney function characterized by decreased glomerular filtration rate, increased serum creatinine or oliguria. "Dpep1-null mice can survive a lethal dose of lipopolysaccharide due to the protein’s role in neutrophil recruitment, which can also affect the severity of acute kidney injury." (PMID 40178918, 2025). "DPEP1 and ferroptosis were identified in the pathogenesis of experimental contrast-induced acute kidney injury (CI-AKI)." (PMID 35108055, 2022). "We further investigated the role of Dpep1 in the folic acid (FA) model, which is a mixed model of acute kidney injury leading to fibrosis development." (PMID 34426578, 2021). "Trials using DPEP1 inhibitors to protect from acute kidney injury may appear far at the horizon given this first preclinical set of data." (PMID 35108055, 2022). "While DPEP1’s nonenzymatic neutrophil-binding activity has been described in relation to sepsis and acute kidney injury with the LSALT peptide being used for COVID-19–related clinical trials, there have been no previous reports connecting its neutrophil-binding activity to cancer." (PMID 40178918, 2025).
colorectal tumor (4 papers, 2016 to 2025). "DPEP1 was identified as one of 281 genes that were upregulated more than 2-fold in at least 60% of colorectal tumor tissues compared with normal colorectal mucosa." (PMID 26824987, 2016). "The level of DPEP1 mRNA averaged about 5-fold higher in colorectal tumor samples than in corresponding normal samples." (PMID 26824987, 2016). "In addition, immunohistochemical results showed that the expression level of DPEP1 increased at higher colorectal tumor stages." (PMID 26824987, 2016).
intraepithelial neoplasia (4 papers, 2021 to 2025). A precancerous neoplastic process that affects the squamous, glandular, or transitional cell epithelium without evidence of invasion. "DPEP1 hydrolyzes dipeptides and metabolizes leukotriene, and it is a marker for the transition from low-grade to high-grade intraepithelial neoplasia." (PMID 41465541, 2025). "Dipeptidase 1 (DPEP1) was upregulated in HIN and CRC compared with low-grade intraepithelial neoplasia and NM." (PMID 34880916, 2021).
osteoarthritis (4 papers, 2021 to 2025). A noninflammatory degenerative joint disease occurring chiefly in older persons, characterized by degeneration of the articular cartilage, hypertrophy of bone at the margins and changes in the synovial membrane. "Modification of DPEP1 function, for example, with its specific inhibitor cilastatin, is therefore expected to have opposing effects on osteoarthritis and hypertension risk." (PMID 37277652, 2023). "Of note is DPEP1 (dipeptidase 1), whose increased expression is causal for osteoarthritis and multisite chronic pain (MCP)." (PMID 34857772, 2021). "As for DPEP1, only a clear link between gene variants and osteoarthritis has been established." (PMID 40862773, 2025). "Given that DPEP1 is causally associated with osteoarthritis, cilastatin could potentially be repurposed to treat osteoarthritis." (PMID 34857772, 2021). "The single nucleotide polymorphism (SNP) rs1126464, a missense variant in the Dipeptidase 1 (DPEP1) gene, has been identified as a risk factor for osteoarthritis (OA)." (PMID 38392197, 2024). "We also detected multiple, pleiotropic colocalizations of DPEP1-related mQTL, especially with osteoarthrosis, hypertension and intake of blood pressure medication." (PMID 37277652, 2023).
COVID-19 (3 papers, 2022 to 2025). A disease caused by infection with severe acute respiratory syndrome coronavirus 2. "Indeed, it was recently reported that neutrophil recruitment to the lungs in ARDS utilizes a unique adhesion molecule (DPEP-1), which is now being targeting in clinical trials for moderate-to-severe COVID-19 (ClinicalTrials.gov NCT04402957)." (PMID 34908534, 2022). "Our future studies will involve determining if DPEP1 expressed on CRC cells can interact with neutrophil and monocytic populations and how DPEP1-positive EVs might enhance this interaction or act as decoys, as we have shown occurs with ACE2-containing EVs in a COVID-19 setting." (PMID 37840781, 2023).